SLC16A10 (solute carrier family 16 member 10)
Description:
Sodium- and proton-independent thyroid hormones and aromatic acids transporter. Mediates both uptake and efflux of 3,5,3'-triiodothyronine (T3) and 3,5,3',5'-tetraiodothyronine (T4) with high affinity, suggesting a role in the homeostasis of thyroid hormone levels. Responsible for low affinity bidirectional transport of the aromatic amino acids, such as phenylalanine, tyrosine, tryptophan and L-3,4-dihydroxyphenylalanine (L-dopa). Plays an important role in homeostasis of aromatic amino acids (By similarity).
Synonyms: MCT10; TAT1; PRO0813
Tractability: Antibody: UniProt places it where antibodies can reach, with high confidence; its Gene Ontology location is reachable by antibodies, with high confidence; UniProt predicts a signal peptide or a membrane-spanning region. PROTAC: ubiquitination databases record sites on it.
Gene: Protein-coding gene on chromosome 6 (111,087,503 to 111,231,194, forward strand). Ensembl gene ENSG00000112394.
Subcellular location: Cell membrane; Basolateral cell membrane
Subcellular location (Human Protein Atlas): Cell Junctions; Vesicles
Pathways (Reactome):
Transport of small molecules: Amino acid transport across the plasma membrane
Gene Ontology:
Molecular function: aromatic amino acid transmembrane transporter activity; L-phenylalanine transmembrane transporter activity; L-tryptophan transmembrane transporter activity; L-tyrosine transmembrane transporter activity; protein binding; thyroid hormone transmembrane transporter activity; amino acid transmembrane transporter activity; transmembrane transporter activity; carboxylic acid transmembrane transporter activity
Biological process: aromatic amino acid transport; thyroid hormone transport; amino acid transport; amino acid transmembrane transport; carboxylic acid transmembrane transport; phenylalanine transport; transmembrane transport; tryptophan transport; tyrosine transport
Cellular component: basolateral plasma membrane; cell junction; plasma membrane
Genetic constraint (gnomAD): Loss-of-function variants: 27 observed, 40.8 expected, observed/expected ratio (o/e) 0.66, 90% interval 0.49 to 0.91. The upper end of that interval is the gene's LOEUF score, 0.91, which puts it in group 3 of 6, group 1 being the genes least tolerant of losing a copy. Missense variants: 529 observed, 669.96 expected, observed/expected ratio (o/e) 0.79, 90% interval 0.73 to 0.85. Synonymous variants: 213 observed, 253.95 expected, observed/expected ratio (o/e) 0.84, 90% interval 0.75 to 0.94.
Homologues: Orthologues: chimpanzee SLC16A10 (99% identical), pig SLC16A10 (90% identical), dog SLC16A10 (89% identical), rabbit SLC16A10 (86% identical), rat Slc16a10 (84% identical), mouse Slc16a10 (84% identical), guinea pig SLC16A10 (76% identical), macaque SLC16A10 (73% identical), tropical clawed frog slc16a10 (65% identical), zebrafish slc16a10 (62% identical), Drosophila melanogaster CG8468 (23% identical), Drosophila melanogaster Mct1 (23% identical), and 11 more. Paralogues in human: SLC16A2 (49% identical), SLC16A8 (24% identical), SLC16A9 (23% identical), SLC16A3 (23% identical), SLC16A11 (23% identical), SLC16A7 (23% identical), SLC16A1 (22% identical), SLC16A14 (22% identical), SLC16A12 (21% identical), SLC16A5 (20% identical), SLC16A13 (19% identical), SLC16A4 (18% identical), and 1 more.
Diseases named in the same sentence as SLC16A10 in open-access papers:
SLC16A10 is named in the same sentence as 36 diseases in open-access papers, as found by Europe PMC text mining. Sharing a sentence is not in itself a finding about the gene and the disease. The quoted sentences say what the papers report.
type 2 diabetes (2 papers, 2020 to 2024). "There was an inverse association with type 2 diabetes risk per SD increase in ln-transformed tyrosine/methionine ratio (beta = −0.141; OR = 0.87 (0.81–0.93)) when including one genome-wide significant instrument located in SLC16A10." (PMID 33352682, 2020).
Cerebral ischemia (1 paper, 2014). Restriction of arterial blood supply to the brain associated with insufficient oxygenation to support the metabolic requirements of the tissue. "SLC16A10 (monocarboxylic acid transporter) has been previously reported to be closely related to cerebral ischemia, whereas Mndal (myeloid nuclear differentiation antigen-like) is an interferon-inducible gene expressed during inflammation." (PMID 25472829, 2014).
diabetes (1 paper, 2015). "Although further studies are required to determine how Slc16a10 and amino acid transport contributes to diabetes pathogenesis, this result indicates that SB transposon mutagenesis can be used as a complementary approach to other T1D gene discovery strategies." (PMID 26438296, 2015).
esophageal cancer (1 paper, 2024). A primary or metastatic malignant neoplasm involving the esophagus. "Research has shown a significant increase in the expression of SLC16A10 in patients with esophageal cancer, which has a negative impact." (PMID 38750066, 2024).
glioma (1 paper, 2021). A benign or malignant brain and spinal cord tumor that arises from glial cells (astrocytes, oligodendrocytes, ependymal cells). "Among these LARs that showed increased expression with increasing WHO grade in both the CGGA and TCGA datasets, HDAC1 is the best-studied LAR in glioma, whereas the potential functions of ESCO2, KAT1, LEF1, and SLC16A10 are unreported in this cancer." (PMID 33718432, 2021).
Hypertryptophanemia (1 paper, 2022). "Deficiency in TDO or in the hepatic aromatic transporter SLC16A10 leads to severe hypertryptophanemia, which can disturb immune and neurological homeostasis." (PMID 36188218, 2022).
lung injury (1 paper, 2024). "Furthermore, SLC16A10 holds promise as a potential target for the treatment of acute lung injury." (PMID 38750066, 2024).
pancreatic cancer (1 paper, 2020). "The expression level of SLC16A10 was down-regulated in 3 independent pancreatic cancer researches.." (PMID 32355273, 2020). "Moreover, SLC16A10 and SLC16A12 were expressed at lower levels in pancreatic cancer." (PMID 32355273, 2020).
psoriasis (1 paper, 2025). An autoimmune condition characterized by red, well-delineated plaques with silvery scales that are usually on the extensor surfaces and scalp. "A key gene SLC16A10 is identified with significant diagnostic and therapeutic potential for psoriasis." (PMID 40919667, 2025). "SLC16A10 represents a promising therapeutic target for guttate psoriasis and can improve the outcomes of existing immune-targeted therapeutic agents." (PMID 40919667, 2025). "Comprehensive in vitro and in vivo experiments confirm that SLC16A10 downregulation alleviates the severity of psoriasis and hyperinflammation." (PMID 40919667, 2025). "SLC16A10 is likely involved in arachidonic acid metabolism in keratinocytes through regulating thyroid hormone homeostasis, contributing to the development of psoriasis." (PMID 40919667, 2025). "Moreover, SLC16A10 may induce one of the sequelae of psoriasis, namely post-inflammatory hypopigmentation, by inhibiting melanogenesis." (PMID 40919667, 2025).
Sepsis (1 paper, 2017). Sepsis is defined as life-threatening organ dysfunction caused by a dysregulated host response to infection. "In contrast, CLP-induced sepsis promoted a 53% decrease in liver Slc16a10 mRNA expression (P < 0.01) and a 49% decrease in liver Slc16a2 mRNA expression (P < 0.05)." (PMID 29118715, 2017). "Herein, we aimed to evaluate the central and peripheral expression of genes involved in the transport (MCT8/Slc16a2 and MCT10/Slc16a10), metabolism (Dio1, Dio2, and Dio3) and action (Thra and Thrb) of TH during NTIS induced by fasting or sepsis." (PMID 29118715, 2017). "However, we did not observe changes in Slc16a10 expression in the liver of CLP-induced sepsis mice." (PMID 29118715, 2017). "In the total hypothalamus, the expression of Slc16a2, Slc16a10, Dio3, and Thrb did not change in these two models fasting and CLP-induced sepsis." (PMID 29118715, 2017).
viral infection (1 paper, 2022). "SLC-mediated transporters for thyroid hormone, ions, amino acids, choline, and energetic substrates (e.g., SLC16A2, SLC41A3, SLC16A10, SLC44A1, and SLC35C2) were downregulated following viral infection." (PMID 36314791, 2022).
tumor (8 papers, 2017 to 2025). "On the other hand, SLC6A20, SLC5A1, SLC4A4, and SLC16A10 were positively associated with OS in 3 tumor types." (PMID 37397501, 2023). "In recent years, it has been discovered that SLC16A10 plays a role in immune regulation and influences tumor development." (PMID 38750066, 2024). "On the other hand, immune system-related genes, including SLC16A10, RNASE1, and RNASE6, function in immune responses, antimicrobial activity, and enhancing anti-tumor immunity." (PMID 38461288, 2024).
cancer (5 papers, 2020 to 2023). A tumor composed of atypical neoplastic, often pleomorphic cells that invade other tissues. "However, studies on SLC16A4, SLC16A10, SLC16A11, SLC16A13, and SLC16A14 in cancer are still lacking." (PMID 34424811, 2021).
infection (2 papers, 2021 to 2025). The state of being infected such as from the introduction of a foreign agent such as serum, vaccine, antigenic substance or organism. "Upon high VL infection, a set of core responsive DEG found in the transporters and VEGF signaling gene groupings (KDR, HPSE, and SLC16A10) were significantly (P < 0.05) downregulated in the fetal placenta." (PMID 40119254, 2025).
neurological disorders (1 paper, 2019). "Surprisingly, all but two genes (FAM129A, SLC16A10) were associated with chemical dependency, addictive diseases, and neurological disorders." (PMID 31827490, 2019).
SLC16A10 also shares sentences with these, for which no sentence is quoted: diabetic cardiomyopathy (2 papers); hypothyroidism (2); Obesity (2); atherosclerosis (1); Autoimmunity (1); chorioamnionitis (1); Glucose intolerance (1); Graves disease (1); Hashimoto thyroiditis (1); Hearing impairment (1); hearing loss (1); heart diseases (1); hyperlipidemia (1); Hypertension (1); hyperthyroidism (1); intrauterine growth restriction (1); ischemia (1); metabolic syndrome (1); periodontitis (1); thyroid (1); thyroid cancer (1).